INS (insulin)
Diseases named in the same sentence as INS in open-access papers (continued):
Sharing a sentence is not in itself a finding about the gene and the disease.
diabetes (continued). "The study adapted a mechanistic model of type 2 diabetes mellitus for T1D by replacing endogenous insulin with exogenous insulin and introducing insulin-dependent feedback on glucose production." (PMID 39771538, 2024). "The Food and Drug Administration (FDA) granted approval for the first genetically modified organism (GMO), Human Insulin Product, in 1982, to treat diabetes." (PMID 38254523, 2024). "The findings of this study emphasize the need for early screening and timely management of DR, particularly in patients with poor glycemic control, long-standing diabetes, and those receiving insulin therapy." (PMID 39867069, 2024). "At presentation to our combined diabetes and obstetric clinic she was commenced on insulin in all pregnancies." (PMID 38461278, 2024). "Duration of diabetes, smoking, hypertension, insulin use, and ApoA1/HDL-C ratio was significantly higher in the CAD group than in the group without CAD (p-values were < 0.001, < 0.001, 0.006, 0.001, and 0.004, respectively)." (PMID 38914982, 2024). "Type-2 diabetes mellitus (T2DM)-induced sarcopenia is intertwined with diminished insulin sensitivity and extracellular matrix (ECM) remodeling in skeletal muscle and other organs." (PMID 38541736, 2024). "These patients had impaired insulin secretion and action at presentation, but with intensive diabetes management, β-cell activity and sensitivity of insulin are significantly improved, allowing treatment to be stopped for insulin within a few months." (PMID 39634998, 2024). "The chemokine signaling mediated by CXCR4 plays a key role in modulating the activity of myeloid-derived suppressor cells that had function in regulating insulin tolerance in diabetes." (PMID 38221932, 2024). "Compared to the original treatment, the dose of basic insulin in diabetes patients after combined use of GLP-1 RA (WMD −2.74 [−4.26, −1.22], p ≤ 0.001) was significantly reduced." (PMID 39072050, 2024). "While there are several drug classes available for managing diabetes mellitus (such as insulin, metformin, sulfonylureas, and glitazones), they have limitations." (PMID 39000033, 2024). "The evidence guiding the use of non-insulin therapies for 6q24-related diabetes is of low quality and more information is needed to make firm conclusions." (PMID 39025920, 2024). "For the cure of diabetes, extensive examination is being conducted to find plant- or synthetic-derived alternatives to insulin, secretagogues, or sensitizers, even if insulin has become one of the most significant therapeutic drugs in medicine." (PMID 38926327, 2024). "While l-glyceraldehyde shows promise in inhibiting tumor growth, d-glyceraldehyde offers potential benefits in inducing insulin production, presenting a novel therapeutic avenue for diabetes management." (PMID 38954014, 2024). "This compound has shown efficacy in insulin sensitization, glucose modulation, and body weight reduction in diet-induced obese mice models of diabetes, as well as in protecting against alcoholic fatty liver disease and gallbladder carcinoma in murine models." (PMID 39489776, 2024). "The identified miRNAs in our study play pivotal roles in various aspects of diabetes pathogenesis, impacting β-cell biology and insulin resistance in insulin target tissues." (PMID 38916841, 2024). "The primary etiology of diabetes is characterized by elevated blood sugar levels due to inefficient insulin utilization within the human body." (PMID 39233892, 2024). "Consistent intake of CAM has demonstrated the ability to lower blood sugar levels and HbA1C, thereby reducing the reliance on insulin in individuals with diabetes." (PMID 39599634, 2024). "Diabetes mellitus (DM) is a chronic metabolic disorder marked by elevated blood glucose levels due to compromised insulin secretion and disrupted glucose homeostasis." (PMID 38612627, 2024).
diabetes (continued). "In this context, diabetes represents a promising candidate for cell replacement therapy, in which stem cell-derived insulin-producing β cells act as the therapeutic source of insulin." (PMID 38867450, 2024). "The quest for a breakthrough in diabetes treatment persisted, setting the stage for one of the most significant medical discoveries of the 20th century: the isolation and production of insulin." (PMID 39691108, 2024). "Conventional treatment, such as dietary changes, insulin therapy, and oral hypoglycemic drugs, are commonly used in combination for diabetes management." (PMID 39452489, 2024). "The most commonly prescribed diabetes medications include: biguanides (72.3%), insulin (42.1%), and GLP-1 RAs excluding OW sema T2D (40.4%)." (PMID 38932879, 2024). "Diabetes management involves regular blood glucose monitoring, multiple insulin injections, maintaining a healthy diet and activity level, adjusting insulin doses to suit life patterns, and regular hospital visits." (PMID 39062227, 2024). "Augmented concentrations of inflammatory biomarkers exhibit a correlative relationship with hyperglycemia and insulin dysregulation, thus bearing potential as predictive indicators for the onset of diabetes." (PMID 38735956, 2024). "Diabetes mellitus (DM) is a disorder characterized by chronic hyperglycemia resulting from failure in insulin secretion, insulin action, or both, generating abnormalities in the metabolism of carbohydrates, fats, and proteins." (PMID 39338300, 2024). "Hypoglycaemia is often regarded as a side effect of diabetes treatment, particularly when using insulin or certain types of oral hypoglycaemic agents." (PMID 39238070, 2024). "The term “diabetes mellitus” describes a complex metabolic disorder characterized by chronic hyperglycemia attributed to defects in insulin secretion and/or insulin action, comprising various diabetes types with distinct pathogenesis and clinical features." (PMID 38550917, 2024). "STZ is a naturally occurring compound used to induce diabetes in experimental models by selectively destroying insulin-producing β-cells in the pancreas through DNA alkylation and oxidative stress." (PMID 39057094, 2024). "High iron levels are a risk factor for type 2 diabetes mellitus (T2DM) and impacts the cardinal features: such as increased insulin resistance, decreased insulin secretion and elevated hepatic gluconeogenesis." (PMID 39396974, 2024). "In contrast, Group 2 consisted of patients with a mean age of 54 years, multiple comorbidities including hypertension (66%) and dyslipidemia (38%), and all patients were diagnosed with diabetes and treated either with oral hypoglycemic medication or insulin." (PMID 39285502, 2024). "This type of diabetes often develops in childhood or adolescence, and individuals with type 1 diabetes must receive lifelong insulin therapy to survive." (PMID 39766863, 2024). "It plays an important role in the process of ketogenesis, gluconeogenesis and insulin synthesis, and is a potential therapeutic agent for metabolic diseases such as diabetes." (PMID 39296716, 2024). "For the endocrine system, kaempferol possesses a therapeutic potential in diabetes management, attributed to its ability to regulate insulin secretion and improve insulin sensitivity." (PMID 39221164, 2024). "AA and eicosanoids regulate diverse physiological and pathological processes, including inflammation, oxidative stress, insulin secretion, the progression of obesity, diabetes, hepatic fibrosis, and cancers." (PMID 39330507, 2024). "For diabetes management, 24% were on basal insulin therapy, and 11% adhered to a basal-bolus insulin therapy regimen." (PMID 38926835, 2024). "Type 1 diabetes mellitus (T1DM) is a chronic autoimmune disease characterized by impaired insulin secretion, while type 2 diabetes mellitus (T2DM) is mainly caused by insufficient insulin secretion or insulin resistance." (PMID 39389941, 2024).
diabetes (continued). "Diabetes mellitus (DM) stands as a paramount global public health issue, marked by hyperglycemia arising from impaired insulin production and distinct altered metabolic pathways." (PMID 38395808, 2024). "These innovations have not only improved glucose management but also enhanced the quality of life of individuals with diabetes, making insulin therapy safer and more effective." (PMID 39734941, 2024). "Glucagon-like peptide-1 (GLP-1), an incretin hormone renowned for its role in post-meal blood sugar regulation and glucose-dependent insulin secretion, has gained attention as a novel treatment for diabetes through GLP-1 receptor agonists (GLP-1-RA)." (PMID 38672620, 2024). "Regeneration of insulin-producing β-cells is an alternative avenue to manage diabetes, and it is crucial to unravel this process in vivo during physiological responses to the lack of β-cells." (PMID 39159974, 2024). "Recent studies using animal models of diabetes have reported that drinking DDW increases the effect of insulin administration and promotes the membrane translocation of GULT4, indicating the possibility of using DDW as a treatment for diabetes." (PMID 39200235, 2024). "On the other hand, Fe overload can reduce insulin sensitivity in insulin-sensitive tissues such as liver, muscle, and fat, and disrupt glucose metabolism, ultimately leading to diabetes." (PMID 38982520, 2024). "This type of diabetes occurs mainly due to low insulin levels or poor cellular responses to insulin, and it is characterized by hyperglycemia." (PMID 39452046, 2024). "Diabetes mellitus is a metabolic disorder characterized by the pancreas leaking insulin or the insensitivity of the body to insulin." (PMID 39458671, 2024). "Improving diabetes education and innovations in insulin formulation and delivery methods are effective methods for improving PIR." (PMID 38803476, 2024). "Researchers often use it to induce diabetes in rats because of its specific toxicity toward the insulin-producing β-cells of the pancreas." (PMID 39943964, 2024). "In diabetics, the ratio of ω3/6 (1/1 to 1/5) improved insulin function by increasing the expression of uncoupling protein 1 in adipose tissue, decreasing FBS, cholesterol, TG, and LDL-c, and increasing glucose tolerance." (PMID 39133724, 2024). "Research has demonstrated that CGA has the potential to reduce fasting blood glucose levels and stimulate insulin secretion in individuals with impaired glucose tolerance, thereby alleviating diabetes." (PMID 38921480, 2024). "Diabetes management typically involves pharmacological interventions, including medications such as metformin and acarbose, as well as insulin therapy." (PMID 39184140, 2024). "Diabetes mellitus (DM) is a chronic metabolic disorder characterized by persistent hyperglycemia resulting from defects in insulin secretion, insulin action, or both." (PMID 39741610, 2024). "Type 1 diabetes mellitus (T1DM), a common chronic condition in children and adolescents, requires lifelong insulin therapy, regular blood glucose monitoring, diabetes education, and collaborative care to achieve favorable treatment outcomes." (PMID 38952745, 2024). "The complexity of diabetes management, which includes insulin therapy, blood glucose monitoring, dietary management, and physical activity, can overwhelm patients and lead to poor adherence to treatment regimens." (PMID 39246894, 2024). "Context-aware technologies, such as hybrid closed-loop (HCL) insulin pumps, are important tools for diabetes self-management." (PMID 38846748, 2024). "Diabetes as a comorbidity and history of insulin use was higher in the IIT group compared with the ISS group but the difference was not statistically significant." (PMID 38698018, 2024). "Diabetes mellitus (DM) is a collection of metabolic disorders marked by high levels of glucose in the blood due to malfunctions in the production or effectiveness of insulin." (PMID 39031306, 2024).
diabetes (continued). "In this article, we will review microfluidic technologies for diagnosing and monitoring diabetes, as well as microfluidic devices for delivering insulin and other pharmaceuticals for the treatment of diabetes." (PMID 38509342, 2024). "A 34-year-old woman was diagnosed with type 1 diabetes mellitus and treated with insulin for 24 years." (PMID 38513803, 2024). "IR is characterized by reduced sensitivity and responsiveness to the effects of insulin, acting as a central factor in the emergence of various health issues, such as diabetes, cardiovascular diseases, and cognitive decline." (PMID 39104819, 2024). "Diabetes mellitus (DM) is a chronic metabolic disease characterized by hyperglycemia, which results from failure of insulin secretion or action." (PMID 39109769, 2024). "A recent study found that high mortality rates from diabetes in low- and middle-income countries are often due to out-of-pocket insulin costs." (PMID 39464844, 2024). "Studies have shown that engineered symbiotic bacteria can reprogram intestinal cells into glucose-responsive insulin-secreting cells to treat diabetes." (PMID 39272484, 2024). "In diabetes management, glucose prediction models can be incorporated into mobile applications and automated insulin delivery systems." (PMID 38611653, 2024). "Whitehall II was one of the first studies to describe biomarker trajectories leading to diabetes diagnosis, including the changes in glucose concentrations, insulin sensitivity, and insulin secretion." (PMID 38060158, 2024). "By virtue of the generated low pH and high H2O2 with GOx in hyperglycemic environment, the dual-sensitive PGI NPs were disassembled to achieve rapid and sustained release of insulin for enhanced diabetes mellitus treatment." (PMID 39310111, 2024). "Two-thirds of the women receiving Troglitazone had improved insulin sensitivity and a greater mean decrease in fasting glucose and protection against diabetes for 8 months after stopping therapy." (PMID 39221169, 2024). "Peptides with DPP-IV inhibition properties can maintain incretin activity and promote insulin secretion, contributing to the management of diabetes." (PMID 39452081, 2024). "This section aims to provide an overview of important studies in the field of gene therapy for diabetes management, emphasizing advancements in insulin gene delivery and manipulation." (PMID 38720379, 2024). "Equally, this database collects generic information around insulin use in individuals with diabetes." (PMID 39358593, 2024). "A small clinical trial in which dextromethorphan (DXM), an NMDAR antagonist, was orally administered to patients with diabetes showed improved glucose tolerance and increased insulin secretion." (PMID 39275180, 2024). "The intricate interplay between diabetes and cancer involves shared molecular pathways like insulin signaling, AMP-activated protein kinase (AMPK), and the mammalian target of rapamycin (mTOR)." (PMID 39333445, 2024). "The Diabetes Treatment Satisfaction Questionnaire and Treatment-Related Impact Measure for Diabetes were used as specific tools to assess secondary endpoints on diabetes satisfaction and compliance in insulin-treated patients in ONWARDS 2, 5, and 6 only." (PMID 39200316, 2024). "Based on the P-values and the opinions of the experts, 5 parameters (renal function, previous cardiac surgery, diabetes on insulin, left ventricle function, pulmonary hypertension) were selected for the cluster procedure." (PMID 38439576, 2024). "Diabetes mellitus, a metabolic disorder, is characterized by elevated blood glucose levels due to the disablement of insulin secretion, defective insulin action, or both." (PMID 39371721, 2024). "Although ethnic- and variant-specific biological mechanisms are not well-understood, several explanations for COVID-19-induced diabetes have been proposed, such as impaired insulin secretion and glucose disposal." (PMID 39358227, 2024).
diabetes (continued). "In the case of diabetes, several preclinical studies have demonstrated the ability of FFPs to modulate blood glucose levels, insulin sensitivity, and metabolic parameters by altering the gut microbiota composition." (PMID 38921380, 2024). "The changes you have had to make in your life because of diabetes (such as diet, exercise, taking insulin or diabetes pills, checking blood sugar)?" (PMID 38500939, 2024). "The anti -diabetes mechanism of quercetin involves inhibition of intestinal glucose absorption, insulin secretion, insulin sensitizing activity, and improvement of glucose utilization in peripheral tissues." (PMID 38403683, 2024). "Among these risk factors, FBG demonstrated the strongest association with the onset of diabetes, followed by postprandial glucose (2hPG), HbA1c, HOMA-IR, and fasting insulin." (PMID 38999920, 2024). "After the resolution of DKA on the first day, all patients with either type of diabetes need insulin therapy for glycemic control due to beta cell dysfunction from glucose toxicity." (PMID 39010018, 2024). "A proxy for severity of insulin resistance during pregnancy was based on insulin treatment; subsequent diabetes was defined as presence of ICD-10 codes and/or antidiabetic medication after pregnancy." (PMID 39497166, 2024). "A mechanism of action phase 1 study showed that the glycemic efficacy of tirzepatide in T2DM results from concurrent improvements in key components of diabetes pathophysiology, including β-cell function, insulin sensitivity, and glucagon secretion." (PMID 39114288, 2024). "Recently, we reported one of the Kv channels, KCNH6 (also called Kv11.2 or hERG2), regulating insulin secretion through its electrical function by studying a large four-generation family with monogenic diabetes." (PMID 38349432, 2024). "Type 2 diabetes mellitus (T2DM) is a systemic metabolic disease characterized by insulin resistance and insufficient insulin secretion, accounting for more than 90% of all diabetes cases." (PMID 39250437, 2024). "Previous studies demonstrated that abnormal expression levels of HSP70 induce inflammation and affect insulin sensitivity as well as glycemic control, making it a potential target for diabetes management." (PMID 39765892, 2024). "A recent meta-synthesis which focused on the use of insulin by older people with diabetes reported that it was often complicated by difficulties with cognition, dexterity and comorbidity." (PMID 38778253, 2024). "In contrast, Cluster 5 had a high proportion of patients receiving insulin treatment, suggesting the presence of severe diabetes with long disease duration." (PMID 38195492, 2024). "Although insulin therapy is the mainstay of treatment for type 1 diabetes mellitus and is a major component of therapeutic regimes for patients with T2D, chronic insulin treatment can have numerous deleterious effects." (PMID 38199575, 2024). "A total of 123 (7.6%) were enrolled in HDHPs and 337 insulin users (20.7%) had at least 1 medical claim for a diabetes-related complication." (PMID 39141389, 2024). "Approximately 30% of patients had medically treated diabetes, of whom about one third required insulin." (PMID 38332036, 2024). "This would involve diabetes educators identifying patients who are eligible to receive the insulin PDA using the electronic medical record and giving the insulin PDA to patients." (PMID 39546450, 2024). "In diabetes, insulin concentration decreases due to pancreatic hormone secretion disorders, while in ketosis, it is low due to chronic hypoglycemia." (PMID 38473200, 2024). "For treating and managing diabetes, VR applications include assisting with carb counting, advice and logging of insulin, encouraging exercise, coaching in lifestyle improvements, and VR telehealth consultations." (PMID 38193465, 2024).